YAP1 (Yes1 associated transcriptional regulator)
Diseases named in the same sentence as YAP1 in open-access papers (continued):
Sharing a sentence is not in itself a finding about the gene and the disease.
cancer (continued). "Previous studies have investigated the upstream cues that trigger YAP1 hyperactivation; however, these efforts focused on the mechanisms that silence the Hippo pathway, with the epigenetic control of YAP1 in cancer being largely unknown." (PMID 39563370, 2024). "KDM3A overexpression is unique among the KDM3 subfamily in cancer, conferring colony formation, migration, invasion, and metastasis through Hippo and YAP1 pathway upregulation Glycolytic genes and glucose transport genes, such as GLUT3/SLCA3, are directly activated by KDM3A and HIF1." (PMID 39299930, 2024). "Targeting YAP1/WWTR1 has therapeutic potential in cancer treatment and regenerative medicine." (PMID 39737174, 2024). "Importantly, YM-positive cancer cells were sensitive to YAP1/TEAD-targeted pharmacologic inhibition." (PMID 39624057, 2024). "Hyperactivation of YAP1 contributes to the development of a broad range of human cancers." (PMID 39271776, 2024). "Correspondingly, we observed pronounced stromal expression of both nuclear and cytoplasmic YAP1 in hybrid-NE SCLC, consistent with the recognized role of YAP1 in the establishment and maintenance of CAFs,78 as well as its activation in cancer cells in close proximity to a rigid matrix." (PMID 38897168, 2024). "YAP1 has been shown to be a potential inducer of lipid droplet (LD) accumulation in cancer cells." (PMID 39630608, 2024). "The efficacy of co-targeting Yap1 in PDAC cells and Cox2 in fibroblasts in vitro and in late-stage PDACs in vivo highlight the codependent functions of Yap1 activation in cancer cells and of Cox2 upregulation in PSCs/fibroblasts in the Gem resistance of 14-3-3ζ+++ PDACs." (PMID 39468013, 2024). "Collectively, these findings reveal that PCYT2 inhibited the metastasis of CRC through the PCYT2/PEBP1/YAP1 axis, supporting the significance of metabolic pathways in regulation on cancer metastasis, and they shed light on PCYT2 as a potential therapeutic target for CRC metastasis." (PMID 39531326, 2024). "In addition, both genetic and pharmacologic inhibition of YAP1/WWTR1/TEAD-dependent transcription re-sensitizes resistant cells to osimertinib as well as preventing the future emergence of persister cancer cells." (PMID 38658677, 2024). "The AURKA-specific inhibitor alisertib, currently under clinical evaluation for various cancer types, suppress YAP1 Ser397 phosphorylation and restores cetuximab sensitivity both in vitro and in PDX models, further emphasising the significance of this event in primary resistance to cetuximab." (PMID 38467828, 2024). "The Hippo signaling pathway depends on two key effector proteins: WW domain-containing transcriptional regulator 1 (WWTR1/TAZ) and Yes1-associated transcriptional regulator (YAP1, also known as YAP), which control organ size, tissue homeostasis, and cancer growth." (PMID 39737174, 2024). "Yap1 plays key roles in modulating mitochondrial function and ferroptosis in various diseases, and it has been proven to have anti‐ferroptosis effects during the process of ferroptosis in cancer cells." (PMID 39400418, 2024). "Increased nuclear YAP1 levels have been found in solid tumors, and various Hippo pathway constituents have been altered in human cancer at the DNA level, including YAP1 and TAZ gene amplification, deletions, or truncating mutations in NF2, LATS1, and LATS2 gene." (PMID 39431199, 2024). "YAP1 protects cancer cells against lorlatinib by regulating the AKT signaling pathway." (PMID 38499647, 2024). "Importantly, YAP1, the AR, and the PSA were strongly associated with CD4+/CD8+ T cells in PC compared with other cancers (respectively)." (PMID 38540274, 2024).
cancer (continued). "YAP1 influences the accumulation of lipid droplets in cancer cells." (PMID 39630608, 2024). "The enriched pathways for downregulated genes in these same conditions uncovered TGFβ/Activin A signaling pathway, fibrosis, vascular endothelial growth factor A signaling, wound healing, autophagy pathways in cancer, proinflammatory/profibrotic mediators, nuclear factor-kB, and YAP1/ECM axis." (PMID 37739089, 2024). "Taken together, these results highlight the crucial role of DPP4 and YAP1/TEAD in driving the emergence of ECM-myCAF from Detox-iCAF through two independent mechanisms, shedding light on the molecular interactions underlying cancer immune escape." (PMID 38561380, 2024). "Moreover, we have provided here a spatial resolution of these interactions by using SpaTalk and showing the TGFβ-mediated crosstalk between Detox-iCAF and cancer cells at the invasive margin leading to YAP1/TEAD activation." (PMID 38561380, 2024). "In addition, in colorectal and gastric (GC) cancer cultures, it was observed that silencing of Yes-associated protein 1 (YAP1), which plays a significant role in the development of numerous carcinomas, led to the downregulation of MALAT1 expression." (PMID 38674413, 2024). "Thus YAP-1 is a promising biomarker not only for EBV-related cancers but also for other virally-induced cancers." (PMID 37476371, 2023). "YAP1 is a key component of the Hippo signaling pathway, and has been shown to be essential for the initiation, progression, and metastasis of many types of cancer." (PMID 37370088, 2023). "Given that the coimmunoprecipitation data showed that WWP2 was an interacting partner of LATS1, we speculated that the cancer-promoting functions of WWP2 might be related to the Hippo-YAP1 pathway." (PMID 36803368, 2023). "Furthermore, in esophageal adenocarcinoma, BRD4 activates the Hippo/YAP1 signaling pathway—one of the primary regulators of cancer aggressiveness and stemness." (PMID 36674511, 2023). "YAP1 and its targets were significantly upregulated in H69 cells in “Adjacent to mix” condition compared to the “Insert” condition in which fibroblasts alone were cultured in proximity to cancer cells (Adjacent to mix vs. Insert)." (PMID 36936987, 2023). "In addition, we showed that USP10 knockdown decreased the levels of YAP1, which is an important positive regulator of migration and invasion in many cancers." (PMID 37184153, 2023). "In addition to ESCs, YAP1 activation in cancer cells increases survival through the induction of BIRC5 and BCL2L1, both of which are important for hESC survival." (PMID 36596852, 2023). "The pancancer analysis also uncovered YAP1 gene amplification in squamous cell, cervical, lung, esophageal, head and neck, and bladder urothelial carcinomas, suggesting that these cancers might also benefit from TEAD inhibitor treatment." (PMID 38067201, 2023). "In PCA, YAP1 only exist in basal/dedifferentiated PCA and stroma cells with little androgen receptor (AR) signaling activation, which contribute to the development of anti-androgen resistance caused by induction of cancer stemness." (PMID 36973255, 2023). "In cancer cells expressing a constitutively active MET, we show a rearrangement of the actin cap filaments, which crash into perinuclear patches associated with spherical nuclei, meandering cell motility and inactivation of the mechano-transducer YAP1." (PMID 37838732, 2023). "Inhibition of BRD4 blunts the YAP1/TAZ-mediated aggressive behavior of TNBC cancer cells." (PMID 37770435, 2023). "Elevated YAP1 expression closely correlates with reduced survival in human cancers." (PMID 37709768, 2023). "As an activator, ZEB1 forms a complex with YAP1 to promote cancer progression." (PMID 36936987, 2023). "In cases with lost ERα expression, YAP1 inhibition could restore the ERα expression that sensitizes the tamoxifen-resistant luminal cancer cell line." (PMID 37894401, 2023).
cancer (continued). "In general, LATS1 plays a critical role in orchestrating the Hippo-YAP1 pathway, thereby subsequently leading to the inhibition of proliferation and invasion in cancer cells, indicating that targeting LATS1 could be a promising strategy for GC treatment." (PMID 36803368, 2023). "A new SYNPO2 transcript lacking the N terminus was found to promote prostate cancer cell invasion by activating RHO-ROCK signaling, indicating that abnormal SYNPO2 can initiate YAP1 nuclear translocation as well as transcriptional activity and promote cancer progression." (PMID 37544991, 2023). "In addition, functional experiments demonstrated that the cancer-promoting function of GNB4 was inhibited after the YAP1–TEADs interaction was disrupted by VP addition." (PMID 37016382, 2023). "Furthermore, glucose‐replete conditions can protect cancer cells from verteporfin, an inhibitor of YAP1 and TAZ." (PMID 37665055, 2023). "We previously have found that YAP1 regulated the cancer stemness and metastasis in TNBC cells." (PMID 36633714, 2023). "CTGF, a cysteine-rich polypeptide, has significant roles in biological mechanisms including angiogenesis, cell proliferation, and cell movement; it is a downstream gene of YAP1, and its expression directly affects the YAP1 pathway, which is important in cancer progression." (PMID 37791063, 2023). "Additionally, our previous work has demonstrated that YAP1 plays an important role in self-renewal of cancer stem cells and its activity is negatively correlated with patient outcome." (PMID 37388902, 2023). "There are versatile mechanisms for Hippo/YAP1 pathway regulation by lncRNAs in various cancers." (PMID 37537569, 2023). "Additionally, inhibition of YAP1 expression significantly blocked the pro-cancer function of GNB4 in H. pylori-induced GC models." (PMID 37016382, 2023). "Since the Pkinase domain is responsible for the phosphorylation of YAP1, the cancer isoform most likely cannot inhibit YAP1, potentially leading to cancer progression, and suggests domain isotypes, created via alternative splicing, are important in human cancers." (PMID 37745975, 2023). "In addition, YAP1 overexpression occurs in a large proportion of human cancers, including ovarian, gastric, liver, and prostate." (PMID 37709768, 2023). "Location 11q22 in the human YAP1 locus is amplified in various human cancers and cancer cell lines." (PMID 37709768, 2023). "Thus, by upregulating both ZEB1 and YAP1, cancer cells are triggering a program that facilitates cancer progression and invasion while still maintaining epithelial markers." (PMID 36936987, 2023). "Moreover, it is known that YAP-1 is upregulated within the nucleus of cancer epithelial cells but its activation in the transition of NFs into CAFs is not yet clear." (PMID 36982752, 2023). "In addition, cancer testis lnc-CTHCC can act as a molecular scaffold to recruit hnRNP K to the promoter of YAP1, thus promoting HCC carcinogenesis and progression by activating YAP1 transcription." (PMID 37564197, 2023). "The carcinogenicity of YAP1/TAZ has been confirmed in many cancers." (PMID 37665055, 2023). "It is also worth noting that YAP-1 may be involved in the development of other diseases in addition to cancer." (PMID 37476371, 2023). "We found a trend toward lower SLC35B2 expression in YAP5SA cell lines compared to controls, indicating that SLC35B2 might not be a direct YAP1 target and molecular regulators independent from YAP1/TAZ might drive SLC35B2 expression in cancer." (PMID 35798875, 2022). "We further screened potential drugs that may be effective in cancer patients with high YAP1 expression." (PMID 36479120, 2022). "We found that YAP1 was highly expressed in cancer tissues, as compared to adjacent normal tissues." (PMID 35685435, 2022). "YAP1 is a Hippo signaling pathway gene, which is amplified in a variety of human cancers." (PMID 35784328, 2022). "It has been reported that YAP1 and cadherins collaboratively affect cancer mechanotransduction." (PMID 35356283, 2022).
cancer (continued). "YAP1 inhibition is of major clinical interest for several cancer types, and it is appealing to speculate that targeting YAP1 could treat persistent HPV infection and/or HPV-positive cancers." (PMID 35170430, 2022). "In addition, CA3 treatment restrained cancer stemness and tumorigenicity of cells derived from GC peritoneal metastases in a YAP1-dependent mechanism." (PMID 36289774, 2022). "Taken together, the data presented here show that YAP1 can be regulated by a novel nonclassical pathway under normoxic conditions, which involves PHD2 and VHL; absence of this regulation under hypoxic conditions stabilizes YAP1 protein and contributes to angiogenesis and cancer progression." (PMID 35937460, 2022). "We compared YAP1 mRNA expression between normal and primary cancer tissues in 23 cancer types." (PMID 36479120, 2022). "Therefore, better defining the role of YAP1 in each cancer type will be a key challenge for future studies about target identification and cancer therapy." (PMID 36479120, 2022). "YAP1 has recently been defined to limit cancer transformation in response to DNA damage." (PMID 35656547, 2022). "Moreover, it has been found that Yes-associated protein 1 (YAP1), which is a major regulator of cancer cell proliferation, was also implicated in sustaining EC growth and tube formation, and controlled EC exosomes release." (PMID 35454874, 2022). "Interestingly, only a fraction of solid tumor cells displayed high YAP1 gene expression and evidence of cancer stemness similar to the profiles of DR-MSCs." (PMID 35356283, 2022). "In addition, YAP1/TAZ engage in crosstalk with other cancer-promoting pathways, such as the Notch pathway, MAPK pathway, and Wnt pathway." (PMID 35672802, 2022). "AZD2858 and varlitinib in clinical trials might be effective in cancer patients with high YAP1 expression." (PMID 36479120, 2022). "Based on the results of this study, we speculate that YAP1 is a cancer-promoting gene, which is highly expressed in malignant tumors of the digestive system and is closely related to poor prognosis." (PMID 35911146, 2022). "Next, we studied the prognostic value of YAP1 by pan-cancer analysis in different databases." (PMID 35685435, 2022). "We investigated the potential role of YAP1 in survival predication from a pan-cancer perspective." (PMID 36479120, 2022). "In PAAD, PRAD and PCPG, YAP1 expression was highly correlated with the expression of most immune checkpoint genes, suggesting that YAP1 may help cancer cells to evade immune destruction." (PMID 36479120, 2022). "In addition, β-catenin-driven cancers require the YAP1 transcriptional complex for tumorigenesis, suggesting the network between the two signaling pathways." (PMID 36479120, 2022). "Notes that miR-375-3p targets YAP1, a nuclear effector of the Hippo pathway, and the down-regulation of miR-375-3p in CRCs also leads to increased expression of Cyclin D1 and Survivin, which promotes proliferation and chemoresistance of cancer cells." (PMID 35922756, 2022). "YAP1 contributes to cancer development in several ways, including promoting malignant phenotypes, the expansion of cancer stem cells and drug resistance of cancer cells." (PMID 35672802, 2022). "In addition to TEAD family members, TBX5 is known to be correlated with YAP1 by forming a complex with YAP and β‐Catenin in initiating the expression of BIRC5 that encodes Survivin and is crucial for cancer cell survival." (PMID 35000271, 2022). "Therefore, when we wish to target YAP1 for cancer treatment, we should at least clarify which isoform of YAP1 is the dominant one before treatment strategies are undertaken." (PMID 35014181, 2022). "YAP1 plays an integral role in self-renewal and maintenance of cancer stemness." (PMID 36045416, 2022). "Thus, we uncover a molecular link between the MAPK-ERK effector CIC and YAP1 in human cells and established YAP inhibition as a strategy to target CIC-deficient cancers." (PMID 36198276, 2022).
cancer (continued). "YAP1 rescues KRAS suppression in KRAS-dependent cancer cells." (PMID 35883668, 2022). "YAP1 was differently expressed in 14 of the 23 cancer types with statistical significance." (PMID 36479120, 2022). "Hippo/YAP1 pathway has emerged as a universal governor and therapeutic target in cancers." (PMID 35281088, 2022). "YAP1 overexpression plays an important role in conferring radioresistance in several cancers." (PMID 34939311, 2022). "Previous studies had shown the evidence of ANKHD1 in the malignant phenotype of cancer cells, including promoting cancer cell proliferation, migration, invasion, and tumorigenesis, by positively regulating of YAP1, JAK/STAT, and STMN1, and negatively regulating p21." (PMID 34743406, 2022). "Is there a way to activate Yap1/Taz signalling spatiotemporally and precisely in specific cell types to promote regeneration without increasing cancer risk?" (PMID 35087046, 2022). "YAP1 is a transcriptional co-activator that interacts with TEADs (transcriptional enhancer factor domain family) and exerts diverse effects on tumorigenesis and cancer progression." (PMID 35407556, 2022). "Therefore, mere nuclear localization cannot fully explain the more robust effect of YAP1‐2 in promoting invasion and metastasis of cancer cells than YAP1‐1 upon EGF treatment." (PMID 35014181, 2022). "Hence, the role of YAP1 in cancer seems to be complex, with our data suggesting that this gene has a direct role in gMDSC genesis." (PMID 35189960, 2022). "Further research should be conducted to study whether aberrant DNA methylation and RNA modifications of YAP1 are involved in cancer development and how they work." (PMID 36479120, 2022). "However, the role of YAP1 in different cancer types and its mechanisms in immune regulation remain to be investigated." (PMID 36479120, 2022). "However, our study found that YAP1 inhibition by verteporfin administration reduced cancer cell viability and stemness and reduced levels of CDH6 and OCT4." (PMID 35356283, 2022). "YAP1 has been demonstrated to play a critical role in the development and progression of cancers." (PMID 35656547, 2022). "Besides CRCs, miR-375-3p targets the Hippo pathway effector YAP1 also in other cancers such as GC, HCC and OVCA." (PMID 35922756, 2022). "YAP1 is a transcriptional regulator that is widely activated in human malignancies and can induce the proliferation, metastasis, stemness and chemotherapy resistance of cancer cells." (PMID 35784328, 2022). "Excessive activation of the downstream effector YAP1 contributes to cancer development." (PMID 35810157, 2022). "YAP1 target COL12A1 (collagen type 12 alpha one chain) is an extracellular matrix protein and is shown to be associated with progressive and recurrent cancers in multiple solid tumors." (PMID 35407556, 2022). "However, some controversies remain regarding the roles of YAP1 in different cancer cell types and models." (PMID 35014181, 2022). "YAP1 could regulate multiple genes involved in angiogenesis through E2F1; it also associates with HIF1α in cancer cells under hypoxic conditions, inducing the VEGF-A promoter." (PMID 35937460, 2022). "Cell adhesion-initiated mechanical strain induces cadherin-dependent YAP1 activation to drive cell cycle entry; in this way, activated YAP1 may represent a master regulator of cancer-driven mechanical strain-induced cell proliferation." (PMID 35356283, 2022). "Thus, the reliance of active YAP1 on high HS expression levels to achieve an efficient drug resistance phenotype can be utilized as a cancer vulnerability." (PMID 35798875, 2022). "Previous studies have indicated that the YAP1 protein is elevated in various human cancers and that dysregulation of YAP1 may contribute to tumorigenesis." (PMID 34082774, 2021). "In addition, in all cases, the percentage of YAP1-positive cells tended to be higher in recurrent cancer than in primary cancer." (PMID 33420363, 2021).